STAT3 (signal transducer and activator of transcription 3)
Diseases named in the same sentence as STAT3 in open-access papers (continued):
Sharing a sentence is not in itself a finding about the gene and the disease.
leukemia (continued). "Therefore, in addition to the possible therapeutic potential of STAT3 inhibitors in cancer treatment they can also be considered for their efficacy in treating infectious episodes in leukemia." (PMID 29593731, 2018). "Upregulation of survivin is mediated by multiple signaling pathways and by the tumor microenvironment including PI3K, MAPK, STAT3, Wnt/-catenin, hypoxia, angiogenesis, and NF-kβ signaling pathways, hence may serve as an important target for leukemia therapy." (PMID 28183295, 2017). "Our results also contribute to clearly separate CD4+ from CD8+ T-LGL leukemia, the first group being characterized by very low frequency of neutropenia and lack of STAT3 mutations." (PMID 28977911, 2017). "In addition, we detected the presence of HSP90- HMWNC that contained BCR-ABL, JAK2, and STAT3 in the high molecular weight region in the cell lysate from Imatinib (IM)-resistant 32Dp210 T315I mouse leukemia cells." (PMID 27551334, 2016). "CD45 is well known in leukemia to be involved in the regulation of the GM-CSF pathway and we observed that PyQ treatment decreased the S727 phosphorylation of the Stat3 transcription factor, and its target genes involved in growth and proliferation were consequently found inactivated." (PMID 27579617, 2016). "Stat3 and Stat5 activities have been found to play essential roles in solid tumors and leukemias." (PMID 25809097, 2015). "Furthermore, in depth study in human leukemia HL-60 cell line showed that TBr induced cell death involved ubiquitin dependent degradation of p-STAT3 with subsequent increase in p-ERK expression." (PMID 25383546, 2014). "Furthermore, TBr was also able to suppress the IL-6 induced phosphorylation of STAT3 (Y705 and S727) in human leukemia HL-60 and K-562 cells." (PMID 25383546, 2014). "All these findings suggested that STAT3 might be associated with MDR and their relation needed to be defined, and this study therefore aimed at deciphering the potential role of STAT3 in chemotherapy resistance in leukemia." (PMID 21677772, 2011). "The extensive body of research on cholesterol’s role in leukemia, including 1,220 publications from 1980 to 2024, highlights its critical involvement in tumor cell survival, proliferation, and treatment resistance, with particular focus on areas like STAT3 signaling and multidrug resistance." (PMID 39917295, 2025). "This process not only reinforces the aggressive characteristics of leukemia cells but also establishes a feedback loop where increased STAT3 activity promotes higher expression of miR-1246, creating a self-sustaining cycle that maintains elevated levels of both miR-1246 and STAT3 activation." (PMID 39572459, 2024). "In addition, the activation of the STAT3 signaling pathway by specific microRNAs, such as miRNA-1246, involves complex cellular and molecular mechanisms that enhance the malignant behavior and aggressiveness of leukemia." (PMID 39572459, 2024). "Thus, we investigated whether ectopic expression of gp130 promotes LMO2-driven STAT3 activity in TF-1 leukemia cells, which highly express other complex proteins except for gp130." (PMID 35805116, 2022). "Mutated STAT3 is a crucial cancer facilitator and leukemia patients with STAT3 mutations carry smaller blood cells than patients without these mutations suggesting that the smaller cells might facilitate cancer progression." (PMID 36438561, 2022). "Taken together, our data demonstrate that Hsp90 inhibition effectively reduces the cell viability and phosphorylation of STAT3 mutated primary LGL-leukemia cells even in absence of cytokine stimulation and its effect is further increased when JAK/STAT signaling is activated with IL2 and IL15." (PMID 29228628, 2017). "This study supports previous work implicating NK cells as the major lymphoid population responsible for eradication of BCR/Abl-driven leukemias and suggests that STAT3-targeting strategies may severely impair NK-mediated antitumor immune responses in BCR/Abl leukemias." (PMID 27148255, 2016).
leukemia (continued). "As tyrosine phosphorylation of STAT proteins induces transcriptional activation through homodimerization, selective inhibition of STAT3/5 phosphorylation in JAK2V617F-harboring leukemia lines suggested that transcriptional targets of STAT3/5 may be silenced selectively in these lines." (PMID 25781882, 2015). "However, until recently, it was unclear whether the adverse effects of STAT3 activation in leukemia were a result of its anti-apoptotic and proliferative effects, or also a result of its immune modulatory effects." (PMID 25914882, 2015). "Interestingly, ROS do not induce tyrosine phosphorylation of STAT3 in SYK-deficient human leukemia cells." (PMID 24662938, 2014). "Thus, strategies designed to understand the transcriptional activity of STAT3 may be important tools for discovering the next generation of anti-leukemia therapies." (PMID 25417721, 2014). "Therefore, the present study provided a molecular mechanism of transcriptional regulation of mdr1 by STAT3, and suggested that STAT3 could be potential target in treating drug resistant leukemia." (PMID 21677772, 2011). "Our group has accumulated a wealth of experience in previous studies on RIG-I, such as RIG-I inhibiting the phosphorylation of STAT3 and AKT, which regulate immune homoeostasis and suppress leukaemia." (PMID 39322862, 2024). "In leukemia, miR-4532 repress normal hematopoietic stem cells (HSC) hematopoiesis via activation of STAT3 pathway." (PMID 39677943, 2024). "In AML, constitutive STAT3 activation was reported in AML patient samples and cell lines and contributes to leukemia cell survival, uncontrolled proliferation, and evasion of apoptosis." (PMID 38806478, 2024). "Here, we provide insights into the cellular processes resulting in the tumor suppressive function of STAT3β in AML and assign a link between STAT3 isoform expression and interferon (IFN) signaling in leukemia cells." (PMID 38806478, 2024). "A study indicated that BMPR1B, Stat3, and BMP4-niche signaling pathways regulate leukemia remission." (PMID 37373155, 2023). "STAT proteins, especially STAT3 and STAT5B have been identified as potential pharmaceutical targets in a range of oncological conditions, including various types of leukemias and solid cancers." (PMID 37207333, 2023). "JAK-STAT inhibitors, such as STAT3 inhibitors or STAT5 inhibitors, revealed an anti-leukemia effect for deno or relapsed/refractory AML." (PMID 36774517, 2023). "Conversely, the misregulation of STATs leads to the development of various diseases, including lymphoma, leukemia, and solid tumors, while STAT3 and STAT5 are the most common signaling proteins that are constitutively activated in leukemia." (PMID 37507383, 2023). "GL can significantly inhibit the growth, migration and invasion of leukemia cells in vitro and in BALB/c mice by down-regulating AKT-mTOR signaling pathway activity and STAT3 phosphorylation." (PMID 36313350, 2022). "In ovarian, liver and leukemia caner, apatinib regulated cell proliferation, apoptosis and EMT by inhibiting VEGFR2/STAT3 pathway." (PMID 34429133, 2021). "Flavopiridol, when used in combination with bortezomib, has also been shown to inhibit STAT3 and STAT5 activity, and induced apoptosis in K562 and LAMA84 leukaemia cell lines." (PMID 33802972, 2021). "DYRK1A has been found to phosphorylate STAT3 Ser-727 in a simian fibroblast (COS-7) cell line and in human B cell precursor of leukemia (MUTZ-5) cells." (PMID 34828406, 2021). "Hyperactivation of JAK2/STAT3 signaling transduces oncogenic signals to promote CML cells growth, leukemia stem cells survival and therapeutic resistance, thus disease evolution." (PMID 33935775, 2021). "In our study, MPT0G449 exhibited strong anticancer activity in leukemia and showed an extensive inhibitory effect on both phosphorylated and total AKT/mTOR, STAT3/5, and MEK/ERK protein expression." (PMID 33986242, 2021).
leukemia (continued). "NF-κB1 and STAT3 were the main factors involved in cytokine release, and both NF-κB1 and STAT3 were proven to be downstream targets of ABL1 in leukemia." (PMID 31396300, 2019). "Inhibition of Bcr-Abl was reported to result in downregulation of STAT3 via JAK and MEK pathways, and ponatinib has been reported to inhibit phosphorylation of JAK2 both in BaF3/T315I cells in vitro and in leukemia models in vivo." (PMID 30959969, 2019). "Concomitantly, EC-7072 was able to downregulate the total amount of LYN, PLCγ2 and STAT3 in CLL cells, further reinforcing the broad transcriptional reprogramming of primary leukemia cells from patients with CLL upon exposure to the compound." (PMID 31681329, 2019). "The signal transducer and activator of transcription 3 (STAT3) pathway is considered a therapeutic target for several aggressive cancers, including various solid tumors, leukemia, and diffuse large B cell lymphoma." (PMID 30420593, 2018). "The Hsp90 inhibitor luminespib was highly effective at reducing the viability of mutant STAT3 NK cell lines and LGL leukemia patient samples." (PMID 29228628, 2017). "The BCR/ABL fusion gene and its downstream signaling pathways such as Ras/Raf/MAPK, JAK/STAT3, and PI3K/AKT pathways play important roles in malignant transformation of leukemia, especially chronic myelogenous leukemia (CML)." (PMID 29312576, 2017). "On the other hand, some studies have shown that STAT3 can enhance NK-mediated immunosurveillance, specifically in a model of BCR/Abl-dependent leukemia." (PMID 27148255, 2016). "It was found that TBr primarily targets STAT3 and ERK signaling during the induction of apoptosis in several human leukemia cell lines." (PMID 25383546, 2014). "SiRNA against STAT3 eradicated established AML and impaired the potential of leukemia-initiating cells; further, LLL12 treatment abolished outgrowth of a patient-derived castrate-resistant tumor." (PMID 24743778, 2014). "Early time treatments with TBr also demonstrated a clear inhibitory effect on the expression of phosphorylated STAT3 and STAT5 in other leukemia cell lines MOLT-4 and K-562." (PMID 25383546, 2014). "Herein, we provide evidence that IDO1 is induced in leukemia cells by IFN-γ in around half of children with AML in a signal transducer and activator of transcription 3 (STAT3)-dependent manner." (PMID 24903009, 2014). "In hematological malignancy, Icaritin showed potent anti-leukemia activity in chronic myeloid leukemia in vitro and in vivo by regulating MAPK, AKT and JAK2/STAT3 signaling pathways." (PMID 24324713, 2013). "This notion is supported by the data in the present study showing that inhibition of STAT3 pathway down-regulated P-gp and partly reversed P-gp mediated MDR in leukemia cells." (PMID 21677772, 2011). "This study aimed to investigate the anticancer potential of three tetracycline analogues chemically modified tetracycline-3 (COL-3), doxycycline (DOX), and minocycline (MIN) in leukemia models, with a particular focus on their cytotoxic effects and modulation of the JAK2/STAT3 signaling pathway." (PMID 42076067, 2026). "A previous study showed that Leonurine plays an anti-leukemia role by inhibiting the proliferation, migration and colony formation of chronic myeloid leukemia cells and promoting their apoptosis through the miR-18a-5p/SOCS5/JAK2/STAT3 axis." (PMID 38267898, 2024). "Here, we show that Th17 cells and IL-17A are highly elevated in Ph+ B-ALL patients, which in turn promote the progression of Ph+ B-ALL by activating BCR-ABL, IL6/JAK/STAT3 and NF-kB signalling pathways and increasing the secretion of the chemokine CXCL16 by leukemia cells." (PMID 38172124, 2024). "The role of STAT1, STAT3, and STAT5 in leukemia development was confirmed in 1995." (PMID 38273387, 2024). "The imbalance of STAT3 isoforms in leukemia cells resulted in enhanced IFN signaling in the absence of STAT3β together with shorter survival of leukemic mice." (PMID 38806478, 2024).
leukemia (continued). "Recently, one group demonstrated that STAT3 regulates glutaminolysis and amino acid (glutamine, glutathione) influx as the anaplerotic reactions to the TCA cycle in leukemia stem cells by promoting expression of MYC, which in turn regulates the transcription of SLC1A5." (PMID 38245798, 2024). "As miRNAs are one of the most potent epigenetic regulators in both health and disease, we hypothesized a role for miRNAs in STAT3 hyper-activation, and thus generated the first high- throughput NGS miRNA dataset in T-LGL leukemia." (PMID 34873301, 2022). "AZD9150, without any delivery agent, was shown to inhibit STAT3 expression in primary AML/MDS leukemia stem cells and to inhibit leukemic cell growth in vitro and in vivo using PDX models of AML/MDS." (PMID 31963765, 2020). "The effective role of STAT3 and STAT5 in maintenance, self-renewal, or transformation of normal HSCs might explain why both proteins are required in the BCR-ABL-dependent leukemia-initiating stem cell population." (PMID 31963765, 2020). "Signal transducer and activator of transcription 3 may also promote leukemogenesis, and active STAT3 has been observed in primary leukemia blasts in a majority of AML patients." (PMID 25914882, 2015). "STAT3 inhibition failed to restrain leukemia progression in immunodeficient mice, demonstrating that the anti-leukemia effects of STAT3 inhibition were likely immune-dependent." (PMID 25914882, 2015). "All leukemia lines tested displayed constitutive phosphorylation of STAT3/5 in the absence of serum, but only in cell lines carrying the JAK2V617F mutation was STAT3/5 phosphorylation inhibited following treatment with JAKi-I." (PMID 25781882, 2015). "While further study and development of STAT3 inhibitors are needed, based on the promising pre-clinical results and evidence of activation in AML, STAT3 inhibition warrants further evaluation in clinical trials in leukemia." (PMID 25914882, 2015). "Although STAT3 activation by G-CSF has been well studied in various leukemia cell lines, we did not observe it here in HT93A cells." (PMID 25805962, 2015). "For example, IL-6 is known to activate STAT3, a key transcription factor in leukemia, leading to the promotion of survival pathways, anti-apoptotic proteins (e.g., BCL-2), and pro-angiogenic factors, all of which contribute to the persistence of leukemia cells in the bone marrow." (PMID 40486651, 2025). "Interestingly, STAT3 inhibition failed to prevent leukemia progression in immunodeficient mice, demonstrating that the anti-leukemia effects of STAT3 inhibition were likely immune-dependent." (PMID 38459166, 2024). "However, in these two studies using leukemia cells and bone marrow-derived mast cells, there was no change in STAT3 protein expression by LicA treatment." (PMID 37238935, 2023). "Leonurine down-regulates miR-18a-5p and enhances SOCS5 expression to curb JAK2/STAT3 signaling pathway activation, impeding CML cells’ proliferation, migration, and colony formation, boosting their apoptosis, and thus exerting a prominent anti-leukemia function in chronic myeloid leukemia." (PMID 36333771, 2022). "Relevant to the connection between oncogenic STAT3 and aberrant lipid metabolism, it has been shown that STAT3-activated CD36 contributes to fatty acid uptake in chronic lymphocytic leukemia cells, which supports a critical role of STAT3 in the regulation of CD36-dependent leukemia." (PMID 33718197, 2021).
leukemia (continued). "To further support the hypothesis that NPQ-C6 was able to inhibit constitutive pYSTAT5 in leukemia cells, we investigated the effects of NPQ-C6 on HEL, a human erythroleukemia cell line in which the JAK2/STAT5/STAT3 signaling pathway is constitutively activated due a JAK2 mutation (V617F)." (PMID 30687103, 2018). "At variance to STAT3 mutated patient, analyzing CD16, CD56, CD57 cell markers no specific immunophenotype distinguishing STAT5b mutated from wild type patients was evidenced among CD4+ T-LGL leukemia." (PMID 28977911, 2017). "However, neither the STATIP1 expression nor its potential to regulate STAT3 activity has been assessed to date in other cancer types, such as leukemia cells." (PMID 25417721, 2014). "Furthermore, targeted STAT3 blocking/TLR9 activation resulted in differentiation of AML blasts to APCs with an activated DC phenotype, increased the ratio of tumor-infiltrating CD8+ T cells to regulatory T cells, and promoted CD8+ T cell dependent regression of leukemia." (PMID 25914882, 2015). "Knockdown of MMP14 in MSCs resulted in a decrease in the expression of P-STAT3 and P-STAT5 in leukemia cells, with no decrease in the expression of total STAT3 and STAT5." (PMID 40121502, 2025). "Intravenous administration of CpG-STAT3 siRNA showed a direct immunogenic effect on leukemic cells indicating that targeted STAT3 inhibition and TLR9 triggering blocks leukemia cell growth by promoting antitumor immunity rather than direct tumor cell killing." (PMID 31963765, 2020). "All mice reconstituted with PTPRT−/− HCK-over-expressing HSPCs revealed hyperphosphorylation of STAT3 but the precise copy numbers of HCK were not ascertained and it is possible that there is a gene dosage effect that is necessary to establish a MPN/leukemia phenotype." (PMID 31065022, 2019).